TRAV1-2 (T cell receptor alpha variable 1-2)
Description:
V region of the variable domain of T cell receptor (TR) alpha chain that participates in the antigen recognition. Alpha-beta T cell receptors are antigen specific receptors which are essential to the immune response and are present on the cell surface of T lymphocytes. Recognize peptide-major histocompatibility (MH) (pMH) complexes that are displayed by antigen presenting cells (APC), a prerequisite for efficient T cell adaptive immunity against pathogens. Binding of alpha-beta TR to pMH complex initiates TR-CD3 clustering on the cell surface and intracellular activation of LCK that phosphorylates the ITAM motifs of CD3G, CD3D, CD3E and CD247 enabling the recruitment of ZAP70. In turn ZAP70 phosphorylates LAT, which recruits numerous signaling molecules to form the LAT signalosome. The LAT signalosome propagates signal branching to three major signaling pathways, the calcium, the mitogen-activated protein kinase (MAPK) kinase and the nuclear factor NF-kappa-B (NF-kB) pathways, leading to the mobilization of transcription factors that are critical for gene expression and essential for T cell growth and differentiation. The T cell repertoire is generated in the thymus, by V-(D)-J rearrangement. This repertoire is then shaped by intrathymic selection events to generate a peripheral T cell pool of self-MH restricted, non-autoaggressive T cells. Post-thymic interaction of alpha-beta TR with the pMH complexes shapes TR structural and functional avidity.
Synonyms: TCRAV1S2; TCRAV7S2; TRAV12
Gene: T-cell receptor variable (V) gene on chromosome 14 (21,642,889 to 21,643,578, forward strand). Ensembl gene ENSG00000256553.
Subcellular location: Cell membrane
Gene Ontology:
Biological process: response to bacterium
Cellular component: plasma membrane
Homologues: Orthologues: chimpanzee TRAV1-2 (84% identical), mouse Trav1 (63% identical). Paralogues in human: TRAV1-1 (82% identical), TRAV20 (34% identical), TRAV36DV7 (33% identical), TRAV7 (32% identical), TRAV13-1 (29% identical), TRAV10 (28% identical), TRAV17 (28% identical), TRAV24 (28% identical), TRAV21 (27% identical), TRAV38-1 (27% identical), TRAV5 (27% identical), TRAV38-2DV8 (26% identical), and 11 more.
Diseases named in the same sentence as TRAV1-2 in open-access papers:
TRAV1-2 is named in the same sentence as 20 diseases in open-access papers, as found by Europe PMC text mining. Sharing a sentence is not in itself a finding about the gene and the disease. The quoted sentences say what the papers report.
COVID-19 (5 papers, 2022 to 2024). A disease caused by infection with severe acute respiratory syndrome coronavirus 2. "A remarkable feature of LLL-specific TCRs isolated from COVID-19 convalescent patients is the almost exclusive use of members of TRAV12 gene family (TRAV12-2 in the case of LLL8)." (PMID 37872153, 2023). "On the other hand, (TRAV1-2+CD8+)MAIT cells were negatively correlated with the disease severity in COVID-19 patients." (PMID 35281000, 2022). "Hospitalized COVID-19 and sepsis cases displayed reductions in the percentage of repertoire occupied by TRAV10, specific to invariant NK T cells, and TRAV1-2 and TRAJ33 usage, in keeping with reductions in MAIT cells." (PMID 35216673, 2022). "The large majority (85%) of HLA-A*0201-restricted, YLQ-specific TCRs from COVID-19 CPs were found to utilize TRAV12-1 or TRAV12-2; none used the nearly identical TRAV12-3 gene segment." (PMID 35013235, 2022).
tuberculosis (3 papers, 2019 to 2025). A chronic, recurrent infection caused by the bacterium Mycobacterium tuberculosis. "The authors reported that among all innate-like T cells assayed, only TRAV1-2+/− MAIT cells significantly expanded in high-risk contacts of tuberculosis cases who never develop evidence for latent infection or active tuberculosis disease after long-term follow-up." (PMID 41206963, 2025). "We conclude that TRAV1-2+ CD8+ T cells with MAIT or MAIT-like features are oligoclonally expanded in the airways during active TB, suggesting that they play a role in the human pulmonary immune response to Mycobacterium tuberculosis." (PMID 31231693, 2019). "It is also possible that the kinetics of expansion of TRAV1-2+ CD8+ cells with MAIT cell-consistent CDR3α‘s varied during the long course of TB disease and anti-tuberculosis therapy that preceded surgical treatment in these medically-complex lung-resection patients." (PMID 31231693, 2019). "Here, we report that a population of pro-inflammatory TRAV1-2+ CD8+ T cells are present in the airways and lungs of healthy individuals and are enriched in bronchoalveolar fluid of patients with active pulmonary tuberculosis (TB)." (PMID 31231693, 2019). "Although the MAIT cell line D466F5 was derived from an active tuberculosis patient, its TCR (TRAV1-2/TRBV6) was not evidenced being biased to M. tuberculosis antigens in this assay or in other reports." (PMID 32582206, 2020). "In contrast to the bronchoalveolar fluid of active TB patients, analysis of TCRα chain usage in granulomas of patients undergoing lung-resection for clinically complicated tuberculosis did not demonstrate dramatic expansions of TRAV1-2+TCRαʼs." (PMID 31231693, 2019).
melanoma (2 papers, 2021 to 2024). A malignant, usually aggressive tumor composed of atypical, neoplastic melanocytes. "In contrast, the second pair of T cell clones were isolated from a patient with melanoma with a distinct TCR: TRAV12-2 TRAJ31, TRBV12-4 TRBJ1-2, recognizing the tumor antigen, NY-ESO-1." (PMID 38561495, 2024).
breast carcinoma (1 paper, 2025). "Additionally, research has shown that MR1-restricted TRAV1-2+ and TRAV26-1+ TCRs identified from the tumor-infiltrating T cells of breast cancer patients specifically respond to some breast cancer cell lines but not to other cancer types." (PMID 40746558, 2025).
Granuloma (1 paper, 2019). A compact, organized collection of mature mononuclear phagocytes, which may be but is not necessarily accompanied by accessory features such as necrosis. "It is therefore notable that even in the resected granuloma tissue, the subset of TCRα‘s with MAIT cell-consistent sequences was enriched among the TRAV1-2+ CDR3α‘s in lung granuloma tissue compared to paired mediastinal lymph node tissue." (PMID 31231693, 2019).
HIV-1 infection (1 paper, 2022). The type species of lentivirus and the etiologic agent of acquired immunodeficiency syndrome (AIDS). "The V-J gene pair TRAV1-2/TRAJ33, the only commonly used paired V-J gene in the HDs, was decreased after HIV-1 infection." (PMID 35351857, 2022).
immunodeficiencies (1 paper, 2021). "To overcome this limitation, we investigated TRAV1-2 (Vα7.2) expression on patients’ PB CD3+ lymphocytes, which has been recently described to be severely reduced in patients with immunodeficiencies caused by V(D)J recombination and DNA repair defects." (PMID 34211466, 2021).
influenza (1 paper, 2021). An acute viral infection of the respiratory tract, occurring in isolated cases, in epidemics, or in pandemics; it is caused by serologically different strains of viruses (influenzaviruses) designated A, B, and C, has a 3-day incubation period, and usually lasts for 3 to 10 days. "Our study utilized a whole live virus assay to measure the kinetics of influenza-specific responses in NK cells, γδ T cells and CD161+TRAV1-2+ MAIT cells (innate-like), and CD8+ and CD4+ T cells (adaptive)." (PMID 33976217, 2021). "Here, influenza+ patients’ PBMCs were incubated with live seasonal H1N1, H3N2, B/YAM and B/VIC viruses to measure influenza-specific innate (NK, γδ, CD161+TRAV1-2+ or MAIT cells) and adaptive (CD4+ and CD8+ T cells) immune responses elicited via IFN-γ production after 18 h." (PMID 33976217, 2021).
primary biliary cholangitis (1 paper, 2025). Primary biliary cholangitis (PBC) is a chronic and slowly progressive cholestatic liver disease of autoimmune etiology characterized by injury of the intrahepatic bile ducts that may eventually lead to liver failure. "For the α chain, Trav10 [S26], Trav16n [S20,26], Trav17 [S27], Trav5‐4 [S26], Traj42 [S20,26] and Traj53 [S26] were associated with Type I diabetes, whereas Trav12‐2 [S28] was associated with primary biliary cholangitis." (PMID 40665793, 2025).
psoriatic arthritis (1 paper, 2020). Joint inflammation associated with psoriasis. "In the context of human PV and psoriatic arthritis, MAIT cells have been evaluated in skin samples and synovial fluid, respectively, using TRAV1-2, CD161 and IL-18Rα as surrogate markers that relatively accurately estimate CD8+ and DN, but not CD4+ and DP MAIT cells." (PMID 33343564, 2020).
pulmonary TB (1 paper, 2019). "In the setting of active pulmonary tuberculosis, we observed striking expansions of TRAV1-2+ CD8+ T cells in the bronchoalveolar compartment." (PMID 31231693, 2019). "Here we report that a population of pro-inflammatory TRAV1-2+ CD8+ T cells are present in the airways and lungs of healthy individuals and are enriched in bronchoalveolar fluid of patients with active pulmonary TB." (PMID 31231693, 2019).
infection (6 papers, 2016 to 2025). The state of being infected such as from the introduction of a foreign agent such as serum, vaccine, antigenic substance or organism. "Collectively, isolation of clone D462-E4 confirms the presence of microbe-reactive MR1-restricted CD8+ T cells that detect infection using an atypical MAIT TCR TRAV12-2." (PMID 27527800, 2016). "On the basis of our findings, we propose that non-TRAV1-2 MR1-restricted TCRs contribute to immune defence against infection primarily by providing more diverse and, in some instances, unique microbial recognition." (PMID 27527800, 2016). "Although both clones recognized the infection, our data show a higher potency of antigen dose in regards to the TRAV1-2+ clone (D426-G11), while both clones displayed similar maximal efficacy (cytokine release)." (PMID 27527800, 2016). "For example, (TRAV1-2+CD8+) MAIT cells, (NCAM1hiCD160+) NK cells, (CD4loCSF1R−CD33−CD14+) classical monocytes, and (CD33− HLA-DMA-CD14+) classical monocytes were associated with asymptomatic infection." (PMID 37795240, 2023). "For instance, the TRAV12-2+ MR1-restricted T-cell clone can recognize infection with S. pyogenes." (PMID 27527800, 2016). "Several common TRA and TRB pairs, such as TRAV1-2/TRAJ33, TRAV21/TRAJ49, TRBV6-4/TRBD2/TRBJ2-3, and TRBV5-1/TRBD1/TRBJ2-7, were consistently detected from the primary infection (PI) through the convalescent phase (HC) and into the reinfection phase (RI)." (PMID 41209021, 2025). "This unique detection pattern of infection and ligand recognition by TRAV12-2+ D462-E4 compared with TRAV1-2+ MAIT cells indicates a greater diversity in microbial MR1 ligands." (PMID 27527800, 2016). "In contrast to TRAV1-2+ MAIT cells, this TRAV12-2-expressing clone displays a distinct pattern of microbial recognition by detecting infection with the riboflavin auxotroph Streptococcus pyogenes." (PMID 27527800, 2016). "In addition, we identified and cloned an MR1-restricted, TRAV12–2+ T cell that, although able to bind the MR1/5-OP-RU tetramer, can recognize infection with S. pyogenes, a pathogen that cannot synthesize riboflavin." (PMID 30006464, 2018). "The TRAV12-2+ T-cell clone responded over a range of S. pyogenes MOI in DCs, while the TRAV1-2+ clone did not respond to this infection." (PMID 27527800, 2016).
TRAV1-2 also shares sentences with these, for which no sentence is quoted: tumor (2 papers); bacterial infection (1); cancer (1); latent infection (1); Sepsis (1); Type I diabetes (1); uveitis (1); Yellow fever (1).